EGFR (epidermal growth factor receptor)
Diseases named in the same sentence as EGFR in open-access papers (continued):
Sharing a sentence is not in itself a finding about the gene and the disease.
cancer (continued). "Given that anti‐CXCL8 and anti‐CXCR1/2 drugs are in advanced stages of clinical development for the treatment of cancers and other diseases, combinatorial therapies involving these drugs and clinically available anti‐EGFR drugs are a real possibility." (PMID 38757578, 2024). "CRISPR knockout screening in human A549 lung adenocarcinoma cells identified 5 EGF-resistance genes, and further RNAi validation showed DUSP1 increased survival of EGF treated cells, providing a novel target for EGFR-overexpressing cancers." (PMID 38816739, 2024). "Erlotinib inhibits epidermal growth factor receptor signaling locally when applied directly to cSCC lesions, targeting cancer cells while minimizing systemic exposure." (PMID 38655092, 2024). "Compared to classic EGFR antibodies used for cancers with varying EGFR conformations, monoclonal antibody 806, targeting epitope 806, has shown promising results in human xenografts and glioblastoma tumor cells." (PMID 38396993, 2024). "ErbB receptors, especially EGFR and ErbB2 have been the primary choices as targets for developing cancer therapies." (PMID 39193326, 2024). "Since the discovery of anti-EGFR therapy for cancer, a variety of epidermal growth factor receptor tyrosine kinase inhibitors (EGFR-TKIs) have been synthesized and approved for clinical treatment." (PMID 38983928, 2024). "Other studies demonstrated that the knockdown of FUT1 reduces EGFR signaling, probably mediated by downregulation of A and/or Lewis Y antigen, making the cancer cells more sensitive to EGFR deprivation." (PMID 39420441, 2024). "To demonstrate this, we examined IC50 (half maximal inhibitory concentration) levels of LUAD cell lines to EGFR inhibitors with respect to the mutational status of EGFR and KRAS as obtained in GDSC (Genomics of Drug Sensitivity in Cancer)." (PMID 39160568, 2024). "These phosphorylated tyrosine residues are bound to several adaptor proteins, and the EGF/EGFR signaling pathway is activated, which plays a critical role in cancer cell proliferation." (PMID 39518052, 2024). "The authors validated the selectivity of the conjugate for cancer cells overexpressing EGFR using confocal fluorescence microscopy." (PMID 39518106, 2024). "In cancer cells, drug-induced resensitization enables perception of paracrine ligands from neighboring cells that reactivate EGFR/ERK within ~1 h after drug treatment." (PMID 39488530, 2024). "Evgueni Nesterov’s group reported the development of the conjugate C11 for sensing EGFR tyrosine kinase, an essential target in cancer treatment." (PMID 39518106, 2024). "Given that more attention is paid to epidermal growth factor receptors (EGFR) in many epithelial cancers, EGFR nanobodies are used in EGFR-overexpression cancer cell treatment." (PMID 38341580, 2024). "EGFR-TKIs are extensively developed targeting EGFR, one well-known oncogene altered in many cancers." (PMID 38460944, 2024). "EGFR is closely related to cell proliferation and development, and its dysregulation leads to the malignant transformation and progression of various cancers." (PMID 39881871, 2024). "In vitro and in vivo, CD73xEGFR targeted the inhibition of CD73/eAdo immune checkpoint and antagonized various cancer-promoting activities of EGFR and CD73." (PMID 39188712, 2024). "Although effective molecular‐targeted drugs available for human use remain limited, anti‐EGFR antibodies have been clinically applied to cancer types that originally express high levels of EGFR." (PMID 39540676, 2024). "The role of the Notch-EGFR crosstalk has been discovered in various types of cancer, including breast, lung, brain cancer." (PMID 39092224, 2024). "Mechanistically, YY1 transcriptionally up‐regulates IL32 secretion from PCs, which then activates the β5‐integrin‐Src‐Akt signaling pathway in EGFR‐mutant cancer cells to confer their TKI sensitivity." (PMID 39435643, 2024).
cancer (continued). "EGFR has been recognized as an effective therapeutic target in various cancer types with approved EGFR tyrosine kinase inhibitors (TKIs) for clinical use." (PMID 38526177, 2024). "It is a member of the epidermal growth factor family and plays a vital role in the progression of the cancer by triggering the EGFR (epidermal growth factor receptor) signaling pathway." (PMID 39654143, 2024). "One study demonstrated that tris(2-chloroethyl) phosphate (TCEP) induces inflammation in HepG2 cancer cells by activating EGFR, which can be counteracted by inhibiting EGFR18." (PMID 38605072, 2024). "For optimal recovery of cancer cells, three epithelial-specific markers (EpCAM, EGFR, and cytokeratin) and one EMT marker (Vimentin) were added." (PMID 38469233, 2024). "Quercetin suppresses cancer cell growth and triggers apoptosis by blocking EGFR-induced phosphorylation and downstream signaling pathways." (PMID 39712495, 2024). "Antibody-dependent cell-mediated cytotoxicity (ADCC) by NK cells is a key mechanism in anti-cancer therapies with monoclonal antibodies, including cetuximab (EGFR-targeting) and avelumab (PDL1-targeting)." (PMID 39791733, 2024). "Epidermal growth factor receptor (EGFR) was found hyper-activated in multiple cancer types, resulting in cancer cell growth, survival, metastasis and therapy resistance." (PMID 38948119, 2024). "Network pharmacology predicted the EGFR/PI3K/Akt/mTOR pathway as a potential key pathway for the anti-cancer effect of black ginseng." (PMID 39200424, 2024). "Enrichment analysis revealed that 54 proteins that directly interact with EGFR were enriched in the signal transduction biological process and in cancer pathways, such as the MAPK signaling pathway." (PMID 38894850, 2024). "In summary, the synthesis and application of clinically approved small-molecule EGFR inhibitors signify a pivotal chapter in the ongoing battle against cancer." (PMID 38611728, 2024). "Our present results suggested that L1CAM is another downstream effector of ADAMTS1 that regulates EGFR activity and cancer progression." (PMID 38263290, 2024). "Numerous human cancers, including breast, liver, colon, and prostate proved to have EGFR overexpression." (PMID 38443456, 2024). "Theoretically, anti‐EGFR antibodies are expected to be effective against EGFR‐amplified cancer, and there are basic and clinical studies suggesting the utility." (PMID 39540676, 2024). "It has been found that EGFR overexpression drives cancer cell proliferation, migration, and invasion and also confers resistance to conventional therapy." (PMID 39453005, 2024). "In conclusion, these results revealed that the effective inhibition of EGFR signaling can reverse the Warburg effect in cancer cell lines and restore OXPHOS." (PMID 38255314, 2024). "Our study is the first to observe the activation of several diverse pathways in cancer cells adapting to targeted EGFR or BRAF inhibition." (PMID 38473364, 2024). "Further evidence supporting the significance of EGFR in TNBC comes from the discovery that high expression of EGFR predicts a poor prognosis in patients with this type of cancer." (PMID 39769315, 2024). "Panitumumab is a fully humanized monoclonal Immunoglobulin G2 antibody that has a high-affinity binding to epidermal growth factor receptor (EGFR), a protein receptor overexpressed in many cancer types in dogs, cats and humans." (PMID 38633313, 2024). "EGFR, despite being a longstanding target for cancer therapies, continues to present challenges due to acquired resistance, necessitating ongoing research into its signaling mechanisms and resistance pathways to improve treatment outcomes." (PMID 39204124, 2024).
cancer (continued). "To further confirm the effector role of Src in PC‐IL32 mediated TKI sensitivity in cancer cells, we performed IC50 TKI experiments using EGFR‐mutated cancer cells treated with CM from PCs in the presence of TKI with or without Src inhibitor Dasatinib." (PMID 39435643, 2024). "EGFR, one of the most common targets for cancer therapy, has been reported to be overexpressed on the surface of a variety of cancer cells." (PMID 38911063, 2024). "In this study, we administered imaging probes through topically administration, which can achieve almost instant imaging of EGFR and PD-L1 by spraying the target area with micro-doses of fluorescent imaging probes and detecting suspected cancer lesions." (PMID 39183296, 2024). "Epidermal growth factor receptor (EGFR) is a key protein in cellular signaling that is overexpressed in many human cancers, making it a compelling therapeutic target." (PMID 39664199, 2024). "To determine the accuracy and LOD of amplifications, we tested reference materials with known copy numbers across six cancer driver genes (EGFR, ERBB2, FGFR3 MET, MYC and MYCN)." (PMID 39682116, 2024). "Yet, the mechanisms by which GPCRs and EGFR are connected to the oncogenic potential of MET signaling in cancer cells are not fully understood." (PMID 39769452, 2024). "Ganglioside expression positively or negatively regulates several types of signaling molecules, including the epidermal growth factor receptor and mesenchymal-epithelial transition factor, in malignant cancer cells." (PMID 39337716, 2024). "Owing to the cellular interaction mediated by the epidermal growth factor receptor (EGFR) on cancer cells, macrophages were recruited to intersperse among the entire hydrogel after culture for 4 days." (PMID 38520648, 2024). "These subsets secrete soluble growth factors, including FGF7 and HGF, which activate MAPK signaling in cancer cells, circumventing EGFR activation." (PMID 38392348, 2024). "Evidence has shown that EGFR signaling activation can increase PD-L1 expression and promote PD-L1/PD-1-mediated immune evasion in EGFR-driven cancer." (PMID 39080767, 2024). "Glutamine deprivation has been reported to induce PD‐L1 expression via the activation of EGFR/ERK/c‐Jun signalling in cancer cells." (PMID 38956970, 2024). "The overexpression of EGFR has been found in numerous types of cancers, including lung, pancreatic, ovarian, neck, brain, and breast, and, in some cases, it is correlated with aggressive phenotypes." (PMID 38612619, 2024). "As such, dimerization was deemed necessary for the interaction of PGRMC1 with protein partners as shown for CYPs (1A2 and 3A4) and the epidermal growth factor receptor (EGFR), involved in signal transduction during cancer proliferation." (PMID 38804287, 2024). "Activation of the EGFR/MAPK/mTOR/AKT/ERK1/2 signaling pathway has been reported to promote cancer cell growth, survival, and metabolism." (PMID 38762741, 2024). "Since the epidermal growth factor receptor tyrosine kinase (EGFR) participates in the growth and progression of cancer, it represents a compelling target for cancer treatment." (PMID 38474579, 2024). "EGFR, a pivotal regulator of cellular processes, undergoes conformational changes upon ligand binding, activating downstream pathways that promote cancer-related activities." (PMID 39193333, 2024). "These advancements in TKI therapy have revolutionized the treatment of EGFR-driven cancers, particularly NSCLC, providing more targeted, effective, and personalized treatment options." (PMID 39337496, 2024). "Recently, it has been reported that the inhibition of EGFR signaling induces excessive intracellular ROS in cancer cells, leading to apoptosis." (PMID 38202856, 2024). "Many studies have initiated targeted cancer therapy strategies based on the specific overexpression of EGFR to cancer cells to concentrate the drug’s toxic effect in the vicinity of the tumour." (PMID 39273378, 2024).
cancer (continued). "EGFR inhibitors (EGFRis) are targeted agents which provided a major advance in the management of many malignant tumors including colorectal cancer, head and neck squamous cell carcinoma, nonsmall-cell lung cancer, breast cancer, and pancreatic cancer." (PMID 38249546, 2024). "This resistance to anti-cancer drugs highlights the urgent need for alternative approaches to effectively combat drug resistance in the EGFR-driven tumors." (PMID 39130636, 2024). "Both iRhom1 and iRhom2 have long been known to regulate EGFR activity, a critical oncogenic signaling in multiple types of cancer, through regulating ADAM17 activity." (PMID 38177179, 2024). "Under the influence of cisplatin, there was an upregulation of EGFR gene, indicating a potential autocrine signalling cascade in cancer cells essential for self-initiated proliferation and activation of the MAPK cascade." (PMID 38674023, 2024). "Several PDA-associated pathways (cell cycle, stress response, Rho GTPase signaling) and cancer driver hub genes (EGFR and JUN) exhibited a cancer-specific rhythmic pattern intricately linked to the circadian clock." (PMID 38716727, 2024). "The median OS for stage IV NSQ cancer was 34.6 months (95% CI, 32.2-36.1 months), 56.4 months (95% CI, not reached), and 12.0 months (95% CI, 11.4-12.8 months), for EGFR-positive, ALK-positive, and WT subgroups, respectively (eTable 3 in Supplement 1)." (PMID 38334998, 2024). "We used AutoPepVax to develop an EGFR-specific pan-cancer vaccine design for GBM, LUAD, HNSCC, and CRAD." (PMID 38675381, 2024). "GLUT1 promotes cancer progression through the regulation of EGFR, cell cycle, and oncogenic signaling pathways." (PMID 38831321, 2024). "LAMC2 is overexpressed in multiple cancers and drives tumorigenesis by interacting with α6β4 and α3β1 integrins, epidermal growth factor receptor (EGFR), and other surface receptors." (PMID 38475740, 2024). "Given the important involvement of the EGFR in cancer pathogenesis, the attempts to combine PDT with EGFR-targeting molecules are currently attracting considerable interest." (PMID 39201395, 2024). "In another study, Liu and colleagues designed a novel nanobody-ferritin platform for targeted drug delivery in EGFR-positive cancer cells." (PMID 38341580, 2024). "Instead, WWP1 modulates RNF11’s ability to downregulate ErbB2 and EGFR, highlighting its complex role in cancer biology." (PMID 39949609, 2024). "The Notch 1-mediated activation of the EMT program implies the downregulation of EGFR signaling cascade with a strong reduction of the expression of oncogene driver leading to the consequent onset of cancer cell resistance to EGFR inhibitors." (PMID 39430758, 2024). "Another study involving SMART-Exos, which are exosomes expressing dual monoclonal antibodies against CD3 for T cells and EGFR for targeting cancer cells, revealed promising results in the context of cancer immunotherapy." (PMID 38794316, 2024). "A luciferase assay was employed to discern the combined effects of Bevacizumab and EGFR-TKI on EGFR-mutant cancer cells." (PMID 39766891, 2024). "Researchers found the inhibition of EGFR nuclear transport can enhance the sensitivity of triple-negative breast cancer cells to cetuximab, providing a promising treatment strategy for this cancer subtype." (PMID 39404930, 2024). "The regulation of cellular EGFR expression and activation depends on complex EGFR trafficking pathways, which significantly influence the biological outcomes of EGFR signaling in cancer." (PMID 39695128, 2024). "Since 2D5 negatively regulates EGFR-mediated signaling and suppresses cell growth in human EGFR-positive cancer cell lines, we analyzed the therapeutic potential of 2D5 in cancer cells using a murine xenograft model." (PMID 38745775, 2024).
cancer (continued). "The combination with the clinical approved monoclonal antibody anti-epidermal growth factor EGFR Cetuximab (Cetuximab-IRDye800) has shown promising results as a specific tracker in different cancer types (i.e., brain, pancreas, head, and neck)." (PMID 39218855, 2024). "We next tested if the attraction of macrophages depended on the activation of EGFR or MEK upon cancer cell-fibroblast interaction." (PMID 39262776, 2024). "Particularly, GE11, a synthetic peptide that binds to EGFR with high specificity and affinity, is effective for targeting cancer cells in vitro and in vivo." (PMID 39453005, 2024). "In the Cancer Cell Line Encyclopedia, BRAF class 3–mutated NSCLC cell lines showed greater sensitivity to EGFR-TKIs compared with BRAF class 2–mutated and KRAS-mutated lines." (PMID 39637338, 2024). "Herein, we undertook a comprehensive review of the development and application of EGFR- and integrin αVβ3-targeting peptides as potential radiometal-labeled radiopharmaceuticals for cancer theranostics." (PMID 39126121, 2024). "By binding to the EGFR, these nanocomposites can deliver therapeutic agents directly to the cancer cells, facilitating the selective elimination of cancer cells while safeguarding normal cells." (PMID 39525484, 2024). "Several authors have demonstrated in various cancer types that C1QBP can positively regulate the autophosphorylation of different RTKs such as EGFR, VEGFR, and IGFR in various cancer types by binding to lipid rafts containing these receptors." (PMID 38473963, 2024). "Gefitinib, acts by interrupting epidermal growth signalling in target cancer cells in the tyrosine kinase domain and is classified as an epidermal growth factor receptor (EGFR) inhibitor." (PMID 39048625, 2024). "According to the gene expression profiles, two cancer cell lines were chosen: BT-20 overexpressing EGFR with wild-type KRAS and ROSE 199 A2/5 bearing C12V mutation in KRAS with wild-type EGFR." (PMID 38374954, 2024). "EGFR plays important roles in metabolism and angiogenesis in cancer, and recent studies have suggested that Aβ interacts with several membrane receptors, including EGFR." (PMID 39434878, 2024). "To address these, we firstly used microfluidic chips to detect the broad-spectrum of triple target combination biomarkers in CTCs of 10 types of cancer patients, including EpCAM, EGFR and Her2." (PMID 38720360, 2024). "The epidermal growth factor receptor (EGFR), frequently overexpressed in malignant cells, is a crucial contributor to cancer proliferation, angiogenesis, inhibition of apoptosis, and metastasis." (PMID 37507626, 2024). "A common feature of rapidly proliferating cells is the increased level of glycolysis, and an activated EGFR pathway was also found to be one of the major regulators of cancer cell metabolism." (PMID 39329717, 2024). "When cancer development depends on EGFR and HER3, the antitumoral effect translates into enhanced growth suppression, especially in combination with chemotherapy in various xenograft models compared to monospecific therapies." (PMID 38835349, 2024). "In our study, more than half of patients with NSQ NSCLC had at least 1 potentially druggable sequence variation, and of these, EGFR-positive cancers were most frequent." (PMID 38334998, 2024). "The epidermal growth factor receptor (EGFR) plays a critical role in regulating essential cellular processes that are frequently hijacked to promote cancer." (PMID 40727266, 2024). "In summary, BsAbs targeting multiple receptors, such as c-MET, EGFR and immune cell receptors, offer a promising approach to cancer immunotherapy by leveraging immune cell cytotoxicity and restoring immune response function." (PMID 39664377, 2024). "Using the combined semiempirical quantum mechanics (QM)/molecular mechanics (MM) free energy simulations, we investigated the reaction between afatinib, the first TCI drug for cancer treatment, and Cys797 in the EGFR kinase." (PMID 38766221, 2024).